FOXP3 (forkhead box P3)
Diseases named in the same sentence as FOXP3 in open-access papers (continued):
Sharing a sentence is not in itself a finding about the gene and the disease.
tumor (continued). "We found that the density of the FOXP3+ regulatory T cell (Treg) infiltrate present in the residual tumor (or its scar) correlated with the pathological response (the less Tregs the more pronounced was the histological response) and predicted cancer-specific survival." (PMID 26369701, 2015). "Furthermore, laboratory researches show CSC tumor spheres lowly express Fas and highly express membrane complement regulatory proteins and FoxP3." (PMID 26161392, 2015). "The role of CD70-mediated immune escape was also demonstrated in non-small cell lung cancer (NSCLC), where CD27+ lymphocytes were found in the tumor microenvironment with a trend towards increased Foxp3 expression and higher CD4/CD8 ratios surrounding CD70+ tumor cells." (PMID 26605342, 2015). "In order to determine tumor infiltration by Treg, Foxp3 immunostaining was performed." (PMID 25352158, 2015). "The role of FOXP3 in tumor cells has been studied for many years." (PMID 26305693, 2015). "Thus, patients with a high number of tumor-infiltrating Foxp3+ cells display an unfavorable prognosis." (PMID 24637664, 2014). "The majority of Foxp3+ cells were found local to poorly differentiated PDA tumor cells." (PMID 24637664, 2014). "Using diverse analytical techniques such as flow cytometry, Western blot, RT-PCR and RNAseq, we confirmed that Foxp3 could be expressed in macrophages in the tumor context." (PMID 25264896, 2014). "However, high densities of tumor-infiltrating CD4+ CD25+ Foxp3+ Treg cells have been correlated with poor survival." (PMID 25105508, 2014). "In the current study, we investigated the distribution of CD4+ CD25+ Foxp3+ Tregs in the peripheral blood and regional lymph node lymphocytes during 4NQO-induced rat tongue carcinogenesis and determined their relationships with tumor progression." (PMID 24264641, 2014). "Overall, recent data is suggesting that a unique effector subset of FoxP3+ cells may exist which influences the tumor microenvironment in a favorable way and contributes to overall antitumor response." (PMID 25365237, 2014). "The mean number Foxp3+ cells per tumor punch was 39 with a median of 27.0." (PMID 24997850, 2014). "FOXP3 expression was originally thought to be restricted to Treg cells, however recent studies have suggested that FOXP3 is also expressed in multiple normal tissues, as well as in a number of tumor types." (PMID 24406338, 2014). "In a naïve context, we did not detect Foxp3 expression in macrophages from any organs, supporting the idea that Foxp3 expression was specifically associated with the tumor context." (PMID 25264896, 2014). "The results suggest that the increased population of CD4+Foxp3+LAP+ Tregs in CRC may play an important role in regulating anti-tumor immune response." (PMID 25268580, 2014). "Here, mature dendritic cells present tumor-specific antigens to peripheral naive FoxP3+ Treg cells, which then proliferate in situ and are thereafter capable of suppressing the anti tumor immune response of CD8+ effector T-cells through heterogeneous mechanisms including IL-10 and TGF-ß." (PMID 25365237, 2014). "In our sample we did not observe any associations between protein expression of FOXP3 and clinical outcome parameters, considering tumor size, lymph node involvement, and nuclear grade." (PMID 24877082, 2014). "However, although data are scant, FOXP3 expression in other tissues has also been observed, including human tumor cells." (PMID 24877082, 2014). "In addition to recruiting Tregs, a group of CD11b(+)CCR8(+) myeloid cells similar to MDSCs recruited by CCR8/CCL1 interaction in urothelial and renal carcinomas also “educate” tumor infiltrating T cells to express FoxP3, a marker for Tregs." (PMID 25110692, 2014).
tumor (continued). "By visualizing DTA-1 with the FITC-conjugated anti-rat IgG2b mAb, it was demonstrated that the tumor-infiltrating CD4+ Foxp3+ Treg population bound predominantly with DTA-1 at 6 hrs after i.t. injection, in parallel with the disappearance of tumoral Treg cells after treatment with DTA-1." (PMID 25105508, 2014). "FoxP3+ cells usually infiltrated the tumor tissue (94.4% positive tumor infiltration)." (PMID 25365237, 2014). "And FoxP3 became a popular single marker for Tregs studies in tumor." (PMID 24827118, 2014). "Additionally, for patients who were lymph node free of neoplasia, a strong FOXP3 expression was verified, most of them being with a strength signal (three crosses), despite being not statistically significant (P = 0.14)." (PMID 24877082, 2014). "TGFβ is reportedly responsible for accumulation of CD4+Foxp3+ regulatory T cells (Tregs) in tumor." (PMID 24416401, 2014). "Our results were in agreement with previous reports that significantly more FOXP3+ Tregs were found in tumor tissues than that in corresponding adjacent normal mucosa; and our data reinforced the fact that a majority of these suppressive Tregs are functional nTregs." (PMID 24938080, 2014). "Meanwhile, very few Foxp3(+) cells were noted in the tumor-regressed lymph node." (PMID 24885770, 2014). "Tumor size was positively correlated to intratumoral FOXP3-positive infiltrate (P = 0.026)." (PMID 24877082, 2014). "Alternatively, the presence of tumor cells in lymph nodes may result in FOXP3+ lymphocytes accumulation through migration, expansion, or peripheral conversion." (PMID 25191901, 2014). "Second, macrophages infiltrating tumors could potentially internalize the protein from Foxp3 expressing cells such as surrounding TRegs from the tumor microenvironment or tumor cells themselves." (PMID 25264896, 2014). "Some evidence also suggests that FoxP3+ Treg cell subpopulations may also be involved in tumor suppressive functions." (PMID 25365237, 2014). "DCs are potent activators of regulatory CD4+ CD25+ Foxp3+ regulatory T-cells that might downregulate an efficient anti-tumor response." (PMID 25340039, 2014). "Emerging evidence indicates that Foxp3 is expressed in tumor cells and may play a role in the tumor evasion of cancers." (PMID 24932293, 2014). "Thus, the original view that FoxP3+ T cells invariably suppress tumor immunity is oversimplified for CRC." (PMID 24827118, 2014). "In this context, we hypothesized that Tregs FOXP3 positive, which were present in the tumor, could act as stimulator of growing in intermediates tumors size (1.5 to 3 cm), in relation to small tumors (less than 1.5 cm)." (PMID 24877082, 2014). "The authors proposed that Foxp3 expressed in cancer cells may modulate expression of chemokine receptors and other genes, and thus influence invasion and metastasis of tumor cells." (PMID 24932293, 2014). "Additionally, Foxp3+ T cells were observed more frequently in juxtatumoral stroma (immediately adjacent to the tumor epithelial cells)." (PMID 24637664, 2014). "Our results that the density of Foxp3 instead of CD8 was perhaps significant for survival may imply that suppressive capacity of Tregs was sufficient to override the anti-tumor immune response initiated by CD8+ TILs in GBM microenvironment." (PMID 24276989, 2014). "Most of the patients (83%) showed a strong staining for FOXP3 protein in the tumor cells." (PMID 24877082, 2014). "Furthermore, the size of CD4+Foxp3+LAP+ Treg population was increased in tumor tissues compared to non-tumor tissues." (PMID 25268580, 2014). "Finally, we detected Foxp3 mRNA in Renca tumor cells from an in vivo IK solid tumor isolated using FACS based on expression of the Cherry fluorochrome." (PMID 25264896, 2014). "In contrast to L1CAM, the role of tumor-related FoxP3 expression in PDAC development is less known." (PMID 24797069, 2014).
tumor (continued). "The properties of FOXP3+ TILs may be affected by the tumor microenvironment, thus the prognostic value of FOXP3+ TILs could possibly be influenced by molecular subtype and interactions with other immune cells." (PMID 25193543, 2014). "In summary, some studies fit with the general notion that FoxP3+ T cells suppress adaptive immune responses and led many groups to pursue strategies to deplete FoxP3+ T cells from patients or mouse with cancer as a means to enhance tumor immunity." (PMID 24827118, 2014). "FOXP3 (forkhead transcription factor 3) is a marker of regulatory T cells (Tregs), whose expression may be increased in tumor cells." (PMID 24877082, 2014). "First, immune tolerance mediated by FOXP3+ lymphocytes may contribute to the survival and proliferation of tumor cells that drain to the lymph nodes and ultimately form foci that are visible under light microscopy." (PMID 25191901, 2014). "Therefore, the accumulation and likely the tumor infiltration of FoxP3+ T-cells mark the presence of tumor-rejecting antigen-specific CD8+ T cells, which in turn serves as a marker for an effective T-cell response." (PMID 25365237, 2014). "We hypothesized that the absolute number of FOXP3+ putative Treg may, in fact, be more relevant in determining effects on the evolving anti-tumor immune response." (PMID 25191901, 2014). "Fluorescent immunohistological studies using double labeling with anti-rat IgG2b mAb (for DTA-1) and F4/80- (for macrophages) or Foxp3- (for Tregs) specific mAbs were performed to determine the mechanisms of DTA-1-dependent depletion of CT26/NY-ESO-1 tumor-infiltrating Treg cells." (PMID 25105508, 2014). "This suggests that FOXP3 may be a tumor suppressor and that inactivation of the FOXP3 gene may contribute to the development of cancer in humans." (PMID 25364468, 2014). "Tumor-infiltrating FOXP3+ Tregs were reported to be increased in a variety of tumors." (PMID 24040244, 2013). "All tumor samples showed CD4+CD25+FOXP3+ Treg infiltration with a combined range of 14-350 cells." (PMID 24244610, 2013). "Our data suggest that FOXP3 may be an effective tumor target in IBC cells however increased anti-apoptotic signaling can lead to immune evasion." (PMID 23341929, 2013). "Further investigations are required to determine whether the heterogeneous subcellular localization of tumor FOXP3 is functionally relevant to the clinical prognosis." (PMID 24649219, 2013). "The accumulation of Tim-3+Foxp3+ CD4 T cells in the cancer nest other than in peritumoral stroma implied that Tim-3+ Tregs could be induced during tumor progression." (PMID 23526963, 2013). "FOXP3 exhibited a heterogeneous subcellular localization in tumor cells (cytoplasm, 31%; nucleus, 26%; both, 6%) and, although cytoplasmic FOXP3 was associated with poor OS (P= 0.058), nuclear FOXP3 demonstrated a significant association with improved OS (P=0.016)." (PMID 24649219, 2013). "Foxp3+ T cells, preferentially attracted to the tumor microenvironment may use the same or additional cues to aid their retention within the tumor mass." (PMID 23874342, 2013). "Why might CD4+Foxp3+ Tregs demonstrate enhanced proliferation in the tumor microenvironment compared to CD4+Foxp3− T cells?" (PMID 23874342, 2013). "Increased infiltration of CD4+ T cells in tumours may also be due to a greatly enhanced number of Foxp3+ regulatory T cells, that would explain the insufficiency of the immune system to adequately attack primary tumours." (PMID 23349906, 2013). "However, it must be emphasized that new drugs to inhibit FOXP3 functions should preserve its antiproliferative activities which are beneficial for the control of tumor cell growth." (PMID 24350059, 2013).
tumor (continued). "In addition, key immunomodulators like tumor-specific CD4+CD25+ forkhead transcription factor Fox P3 (FoxP3) positive regulatory T lymphocytes also known as regulatory T-cells (Tregs) are spontaneously induced by many types of cancer." (PMID 23537231, 2013). "FOXP3 was expressed in the nucleus of lymphocytes, representing Treg infiltration, whereas a heterogeneous subcellular localization of FOXP3 was observed in tumor cells (i.e., the cytoplasm and/or nucleus)." (PMID 24649219, 2013). "Finally, we analyzed the overall survival of patients with low or high Foxp3+ Treg infiltration in the tumor in comparison to the survival of patients with low or high Foxp3 expression of their cancer cells." (PMID 23382847, 2013). "Foxp3+ expressing cancer cells were found in 60 out of 65 tumor cases (n = 60/65, 92.3%)." (PMID 23382847, 2013). "Increased levels of FoxP3 may also indicate that cytolytic T cells are also present at increased numbers within the tumor." (PMID 24376535, 2013). "In this setting, we could show that the transferred cells acquired CD25 and Foxp3 at significantly higher levels in draining lymph nodes, compared to contralateral lymph nodes of tumor-bearing mice, or to the lymph nodes of tumor-free mice." (PMID 23986759, 2013). "Additionally, GARP is part of a positive feedback loop with FOXP3 in Tregs, which are known to maintain a suppressive tumor microenvironment and prevent an effective immunological response." (PMID 23382860, 2013). "There is ample evidence supporting the hypothesis that tumors convert CD4+FoxP3− (Tconv) into CD4+FoxP3+ (iTreg) by tumor-derived signals, while others suggest that nTregs are recruited and/or expanded by the tumor." (PMID 23720663, 2013). "In a murine model of breast cancer, siRNA-mediated silencing of IDO in vaccinating DC enhanced the ability of these cells to stimulate T cell proliferation and CTL effector function, decreased the induction of CD4+ CD25+ FOXP3+ Tregs, and led to enhanced control of tumor outgrowth." (PMID 23874338, 2013). "Whether in Tregs or in tumor cells, FOXP3 expression plays an immunosuppressive role at the tumor site." (PMID 23759077, 2013). "Accumulating evidence indicates a pivot role of Akt/mTOR pathway in regulating CD4 + Foxp3+ regulatory T cells in tumor microenvironment.Therefore, targeting mTOR by rapamycin may be a promising therapeutic strategy for ASCC." (PMID 24124460, 2013). "Recently, it was shown that FOXP3 is not only expressed in Tregs but also in tumor cells of cancer patients; its expression level and function may represent a new mechanism of immune evasion in cancers." (PMID 23759077, 2013). "The data clearly indicated that the TCR repertoires of tumor-infiltrating Foxp3− and Foxp3+CD4+ T cells are distinct, implying that at least in the case of carcinogen-induced tumors, conversion of conventional T cells is not a significant cause of intra-tumoral Treg enrichment." (PMID 23874342, 2013). "Moreover, if these highly proliferative CD4+Foxp3+helios+ cells are, as this study suggests, suppressive within the tumor microenvironment then the available evidence favors intra-tumoral expansion of tTreg as a major mechanism of Treg enrichment in tumors." (PMID 23874342, 2013). "We also found more Foxp3+ cells in tumor tissue compared to normal skin." (PMID 23667456, 2013). "However, among the immune cells recruited by SLC to tumors, the CD25+ Foxp3+ regulatory T cells (Tregs) compromise the anti-tumor effects." (PMID 24304581, 2013). "Indeed Foxp3+ T cells manage to successfully pervade, and often dominate the tumor-specific immune response; Foxp3+ to Foxp3− T cell ratios in the range 0.5–1:1 have been described in some tumors." (PMID 23874342, 2013). "Importantly, combined OK-432- and PSK-activated DC/tumor showed superior efficacy in inhibiting CD4+CD25+Foxp3+ T cell generation, in comparison to those single activated or un-activated DC/tumor." (PMID 23555011, 2013).
tumor (continued). "Given that other cells in addition to T cells express FOXP3 (e.g., tumor cells and B cells), the significance of that work, while interesting, remains unclear." (PMID 24244610, 2013). "By contrast, nuclear FOXP3 expression in tumor cells, which was associated with improved OS in this study, was significantly enhanced in patients with absent or low infiltration of FOXP3+ lymphocytes." (PMID 24649219, 2013). "Furthermore, predominant cytoplasmic FOXP3 staining of tumor cells was demonstrated in several types of cancer, although its relevance has not been clarified." (PMID 24649219, 2013). "Thus, small molecules targeting HAT/HDAC or disrupting their interactions with FOXP3 are interesting candidates for the regulation of Treg function in vaccines and tumor therapies." (PMID 24350059, 2013). "FOXP3 may propagate crosstalk between tumor cells and their immunological microenvironment, e.g., involving signal transducer and activator of transcription 3 (STAT3), leading to tumor-induced immunosuppression, including the induction of Tregs." (PMID 24649219, 2013). "Furthermore, these tumor-infiltrating CD4+Foxp3− T cells were able to suppress T-cell proliferation in vitro in an IL-35-dependent fashion, indicating that tumor establishment led to the generation of iTr35 cells." (PMID 24151492, 2013). "Thus, in studies aimed at analyzing the impact of Tregs on tumor progression, it is critical to take the localization of Foxp3+ Treg into account." (PMID 22890822, 2013). "FOXP3 in tumor cells may have distinct biological activities and prognostic values according to its localization, which may help establish appropriate cancer treatments." (PMID 24649219, 2013). "Indeed, since FOXP3 Tregs are immunosuppressive cells, many studies have reported that their abundant presence in tumor infiltrates leads to reduced survival in cancer patients." (PMID 23341929, 2013). "Accordingly, a recent analysis of Treg subsets in Her2/Neu-expressing mammary tumor-bearing mice revealed the existence of a Cy-sensitive CD4+Foxp3+CD25+ subset with tumor-seeking migratory phenotype, characteristic of amTregs, and capable of high avidity T-cell suppression." (PMID 24133490, 2013). "Moreover, pancreatic tumor-derived TGF-ß was shown to activate Foxp3 expression in tumor cells themselves." (PMID 24133490, 2013). "Cancer cells expression of Foxp3 followed by secretion of immunosuppressive cytokines into the microenvironment of the tumor tissue may give the tumor a powerful tool to circumvent immunological destruction." (PMID 23382847, 2013). "Our results clearly explain the function of FOXP3 as a tumor suppressor." (PMID 24155921, 2013). "These analyses showed that in both tumor microenvironments, IL-10 treatment caused a significant increase of CD4+granzyme+ T cells with a concomitant decrease of CD4+CD25+FoxP3+ Treg, reminiscent of what observed after vaccination with gp10025-33 peptide-pulsed DC." (PMID 23663506, 2013). "There may be preferential migration of Foxp3+ T cells to tumors in response to chemokines expressed by tumor cells and stroma." (PMID 23874342, 2013). "In addition, emerging evidence suggest that FOXP3 is variably expressed in T cells during activation, as well as on tumor cells." (PMID 23758773, 2013). "Although tumor suppression by FOXP3 has been investigated by many researchers, regulatory proteins that functionally modify FOXP3 are still unknown." (PMID 24155921, 2013). "We have previously demonstrated that FOXP3 is an effective immunotherapeutic target, and vaccination of mice with murine FOXP3 mRNA-transfected dendritic cells (DCs) elicits FOXP3-specific T cell responses and enhances tumor immunity." (PMID 23341929, 2013). "Previous studies suggested that tumor-expressed FOXP3 may be useful as a clinical prognostic marker." (PMID 24649219, 2013).